IL10 (interleukin 10)
Diseases named in the same sentence as IL10 in open-access papers (continued):
Sharing a sentence is not in itself a finding about the gene and the disease.
malaria (continued). "However, antigen-specific IL-10-producing Th1 cells were found in cord blood of babies whose mothers had malaria during pregnancy, suggesting that these cells might be able to influence anti-parasitic immunity from very early in life." (PMID 25352846, 2014). "However, children responding to a homologous cys2 DBLα-tag induced IL-10–secreting CD4+ T cells during acute disease but IFN-γ–secreting CD4+ T cells 16 wk after an acute malaria episode, suggesting that a stable population of effector memory Th1 cells was maintained." (PMID 24453249, 2014). "Hence, the kinetics of the emergence of IL-10-producing Th1 cells during malaria may be critical in determining the impact they have on the outcome of infection." (PMID 25352846, 2014). "Also, it is important to highlight that high ANXA1 expression in some lymphocytes and other leukocytes might had influence on the levels of IL-10 in malaria patients." (PMID 24359168, 2013). "Thus, we favor the hypothesis that during malaria monocytes differentiate into an inflammatory stage producing high levels of pro-inflammatory cytokines and low levels of IL-10." (PMID 22745844, 2012). "In the present study, we examined serum cytokines at the time of acute malaria and found a similar pattern in vivo with a decrease in cytokines/chemokines associated with severe malaria (IL-1ra, IP-10 and IL-8) and an increase, albeit not statistically significant, in IL-10." (PMID 23133692, 2012). "It has been also shown that cytokines play an important role in the immunopathology of malaria and many field studies have described an association of specific cytokines with severity of disease, in particular IL-2, IL-12, IFN-γ, IL-1β, IL-6, TNF, IL-4, IL-10, MIP-1β, and TGF-β." (PMID 22280502, 2012). "Our study shows that IL-10, IP-10 and RANTES are increased upon infection with P. falciparum and therefore might be valuable for diagnostic purposes during pregnancy-associated malaria." (PMID 23155405, 2012). "On the other hand, given its well-described role as a B cell growth and differentiation factor and its role in controlling production of malaria-specific IgG, long term maintenance of memory B cells may well benefit from the sustained antigen-specific IL-10 responses." (PMID 21347351, 2011). "Thus, the role of IL-10 in severe malaria remains undefined." (PMID 21447146, 2011). "Interestingly, a higher ratio of IL-6 to IL-10 was also observed in sera of Vietnamese patients with fatal severe malaria, vs. those with severe disease who survived, implicating unbalanced pro-inflammatory and anti-inflammatory cytokine production as a risk factor for fatal malaria." (PMID 20591122, 2010). "However, the cellular source of IL-10 in human malaria cases was, until now, ill defined." (PMID 19343213, 2009). "Our co-culture system may well reflect the processes occurring in vivo during malaria-infection, and explain the elevated levels of CD4+CD25hiFoxp3+ T cells observed in malaria-infected individuals and the association of IL-10, TGFβ and IL-2 with their induction." (PMID 19680449, 2009). "In addition, our results imply that the evolutionary trajectory of malaria virulence may be altered by changes to the IL-10 milieu of a host population." (PMID 18447949, 2008). "In humans, malaria during pregnancy results in elevated levels of numerous cytokines, including IFN-γ, TNF-α, IL-4, IL-6, IL-10, and CXCL9 in peripheral circulation, with some of these cytokines linked to increased risk of pregnancy loss." (PMID 40470930, 2025). "Our analysis of the cytokine profiles revealed that children with an episode of uncomplicated malaria had reduced frequency of IFN-γ–secreting T cells and upregulated IL-10–producing T-cell subsets." (PMID 41285032, 2025).
malaria (continued). "Further studies are required to investigate the age-dependent induction of other regulatory cell responses during malaria, such as Tr1 CD4 T cells which co-produce IL10 with IFNγ and dominate the CD4 T cell compartment during malaria infection." (PMID 41027884, 2025). "We found a strong inverse correlation between IL-10 production by EBV-specific CD8 T cells and cytotoxic function, suggesting a link between malaria-mediated immunosuppression and control of EBV-infected cells." (PMID 41285032, 2025). "Examining malaria-experienced individuals for common markers across all assays, 4-1BB+, CTLA-4+, CX3CR1+, NKG2C+, TIM-3+, and Siglec-7– NK cells were enriched for IL-10 production." (PMID 40337867, 2025). "It is a more potent T-regulatory cytokine than IL-10 in malaria immunity, and higher levels of TGF-β are inversely proportional to severe forms of malaria." (PMID 38404582, 2024). "In the current study, participants with malaria had higher TNF‐α/IL‐10, TNF‐α/TGF‐β, IFN‐ɣ/TGF‐β, and IL‐1β/TGF‐β, but lower IFN‐ɣ/IL‐10, IL‐1β/IL‐10, and IL‐6/TGF‐β ratios than those in the control group." (PMID 39240033, 2024). "Since it has been shown that blood levels of cytokines are altered during malaria, levels of the serum cytokines TNF-α, IFN-γ, IL-10, and IL-6 of uninfected and PbA-infected mice at day 7 post-infection were determined using CBA analysis." (PMID 38787228, 2024). "Malaria‐infected children had relatively higher TNF‐α (p < .001), IFN‐ɣ (p < .001), IL‐1β (p < .001), IL‐6 (p < .001), GM‐CSF (p < .001), and IL‐10 (p < .001) levels than uninfected participants." (PMID 39240033, 2024). "Severe malarial anemic children had elevated TNF‐α (p < .001), IFN‐ɣ (p < .001), IL‐1β (p < .001), IL‐6 (p < .001), GM‐CSF (p < .001), and IL‐10 (p < .001), but lower IL‐3 (p < .001) and TGF‐β (p < .001) than those with uncomplicated malaria." (PMID 39240033, 2024). "IFN-γ, IL-2, IL-5, IL-6, and IL-12 were increased in mild malaria, whereas TGF-β, TNF, IL-10, and IL-1β were particularly elevated in cerebral malaria." (PMID 38774541, 2024). "The type I IFNs play a more complex role during malaria, such as promoting parasite clearance in the liver stage, suppressing IFNγ production of parasitic-specific CD4+ T cells, and promoting IL-10 producing Th1 cells." (PMID 38715061, 2024). "Malaria presents with enhanced release of TNF‐α, IFN‐ɣ, IL‐1β, IL‐6, GM‐CSF, and IL‐10, but downregulates IL‐3 and TGF‐β in Ghanaian children." (PMID 39240033, 2024). "Distinct cytokine profiles in malaria and schistosomiasis coinfections were TNF, IFN-γ, IL-4, IL-5, IL-10, TGF-β, and CXCL8." (PMID 36716305, 2023). "Increased IFN-γ, IL-4, IL-10, IL-27, CXCL10, and CX3CL1 levels were observed in malaria monoinfection compared to HIV virus monoinfection." (PMID 36716305, 2023). "In this issue of the JCI, Edward, Ng, and colleagues identified a conserved transcriptional signature that distinguished Tr1 (IL-10+IFN-γ+) from Th1 (IL-10–IFN-γ+) cells in human and mouse malaria." (PMID 36594472, 2023). "For intestinal parasite infections, increased TNF, IL-1, IL-6, IL-10, CCL2 and decreased IL-4, IL-17, TGF-β were observed in malaria coinfections compared to intestinal parasite monoinfection." (PMID 36716305, 2023). "Distinct cytokine profiles in malaria and human African trypanosomiasis coinfections were TNF, IFN-γ, IL-6, and IL-10." (PMID 36716305, 2023). "A significant decrease in IL-10 levels in malaria and HIV coinfections compared to malaria monoinfections was observed in two studies." (PMID 36716305, 2023). "Most of the cytokines that were investigated in malaria and other parasite coinfections were TNF, IFN-γ, IL-2, IL-4, IL-6, and IL-10." (PMID 36716305, 2023). "Based on this supposition, patient plasma containing different amounts of IL-10 was selected, and TNF was used as an inflammation readout upon Hz simulation of whole blood from malaria naïve donors." (PMID 37060041, 2023).
malaria (continued). "During this early phase of malaria, expressions of TNF-α and IL-10 were static in all splenic cells." (PMID 36839438, 2023). "Our results explain, at least in part, the sexual dimorphism in the immune response in malaria since DHEA administration decreased IFN-γ and IL-10 concentrations only in intact females." (PMID 37628731, 2023). "Increased TNF, IFN-γ, IL-6, IL-10, IL-17, CCL2, and CCL3 levels and decreased IL-7 levels were observed in malaria monoinfection compared to dengue virus monoinfection." (PMID 36716305, 2023). "For instance, increased levels of IL-12, IL-6, IL-10, IL-1β and IFN-γ have been identified during severe malaria whereas low levels of 1L-12p70, IL-10, IFN-α, and IFN-γ have been associated with SM in children." (PMID 37525227, 2023). "Distinct cytokine profiles in malaria and HBV coinfections were TNF, IFN-γ, IL-4, IL-6, IL-10, IL-12, and CCL2." (PMID 36716305, 2023). "Although a previous study reported co-expression of TNF and IL6 by IL-10 producing Bregs138, only a small fraction of IL-10+ Bregs co-produced IL6 during malaria, and there was minimal co-expression with TNF." (PMID 37968278, 2023). "Distinct cytokine profiles in malaria and intestinal parasite coinfections were TNF, IL-2, IL-4, IL-6, and IL-10." (PMID 36716305, 2023). "Heligmosomoides polygyrus infection results in a strong IL-10 and TGF-β1 response, and thus, suppresses the protective efficacy of the vaccine against malaria challenge, indicated by the inhibited levels of malaria-specific IgG, IgG1, and IgG2a in mice." (PMID 36297220, 2022). "For Vδ1+ T cells oligoclonal expansions that often dominate the malaria γδ T cell response by IL-10 and IFN-γ secretion are evident in children and adults living in malaria-endemic areas." (PMID 35250979, 2022). "Given the well-defined pathologies that can be measured in the mouse models of malaria there have been several studies confirming the importance of immunomodulatory cytokines such as TGF-β and IL-10 against malaria pathogenesis." (PMID 36146602, 2022). "This translated into much weaker correlations of IL-10 with TGF-β1, TGF- β3, and IL-9 than seen between the latter, thus making it a less reliable marker of malaria control." (PMID 36293524, 2022). "The second cluster of markers was composed by IFN-γ, creatinine, IL-1β, direct and indirect bilirubin, CXCL10 and IL-10, with heightened MDP values being observed in both the group of individuals with either asymptomatic or symptomatic malaria." (PMID 34727121, 2021). "Significantly lower cytokine responses (IL-1β, IL-6, IL-10, TNF-α and IFN-γ) to LPS and Staphylococcus aureus were observed among participants with asymptomatic malaria compared to controls." (PMID 34177883, 2021). "While children with asymptomatic malaria have increased IFNγ, TNF and IL-4 levels, IL-10 and CXCL10 were elevated in asymptomatically infected pregnant women." (PMID 33407502, 2021). "Patients with bacteremia had lower circulating IL-10, TNF-α and IFN-γ and higher IL-6 concentrations, compared to clinical malaria." (PMID 34177883, 2021). "Therefore, this tendency of an increased risk of malaria among carriers of rs1800890 SNP in IL-10 gene, could results from changes that do not allow adequate modulation of inflammatory responses since IL-10 is an anti-inflammatory cytokine." (PMID 33593344, 2021). "Extending our approach to participants with severe malaria, we found that MDP levels of IL-10, IL-12p70, AST, ALT, and indirect bilirubin were directly associated with parasitemia." (PMID 34727121, 2021). "The data also highlights IL-10 and CXCL9 as important factors in both asymptomatic and acute malaria and add to the understanding of asymptomatic P. falciparum infections in malaria-endemic areas." (PMID 33407502, 2021). "For cytokines IL-6, IL-1RA, IL-10 and IL-11 and chemokines CXCL1, CXCL8, CXCL10, CCL3 and CCL2, significantly higher concentrations were found in plasma samples of malaria patients compared to healthy controls." (PMID 34359826, 2021).
malaria (continued). "We have found that many of the cytokines involved in malaria (TNF-α, IFN-γ, IL-4, and IL-10) play a double role, as a friend or as an enemy." (PMID 34790829, 2021). "Cytokine concentrations were significantly higher in clinical malaria, whereas the IL-10 and TNF-α over parasite density ratio were higher in asymptomatic malaria." (PMID 34177883, 2021). "During blood-stage malaria, CD4+ T cell-intrinsic IFN-I signaling induces T-bet and Blimp-1 expression, thereby promoting IL-10+ Tr1 responses in mice as well as in humans." (PMID 32265335, 2020). "For children with microscopic asymptomatic malaria, IL-6 was found to positively correlate with TNF-α (r = 0.59, p < 0.0001), IL-4 (r = 0.39, p = 0.017), and IL-10 (r = 0.50, p = 0.002)." (PMID 33281757, 2020). "IL-10 also strongly inhibits the production of cytokines such as TNF, IL-I and IL-6, which are involved in malaria pathology." (PMID 32758231, 2020). "In some cases, a surge in inflammation due to malaria infection leads to severe or moderate malaria, specifically due to higher levels of circulatory pro‐inflammatory cytokines, such as TNF and IL‐6, but IL-10 regulates the outcome." (PMID 32033605, 2020). "Here we show that malaria SPZ induce Mφs which express PD-L1, produce IL-10 and show reduced motility." (PMID 32898164, 2020). "In this study, it was confirmed that the baseline levels of inflammatory cytokines IL-6, IL-10, IL-12, and TNF-α in malaria-infected donor blood (parasitaemia, 515-1877 parasites/μL of blood) were significantly higher compared to noninfected controls." (PMID 33195706, 2020). "Malaria induces secretion of IL-10 from DCs, providing an immunosuppressive environment that skews the development of CD4 T cells and dual blocking IL-10 and PD-1 signaling in mice restores T cell function." (PMID 32793231, 2020). "CD4 T cells in adults from malaria-endemic areas also express cytokines of multiple lineages including IFN-γ, IL-10, and IL-21, even in cells with a Tfh-like phenotype." (PMID 32634740, 2020). "Patients with malaria-HBV coinfection presented elevated concentrations of multiple variables such as IFN-γ, TNF-α, IL-4, IL-10, CCL2, and reduced levels of IL-12 and creatinine levels when compared to those with asymptomatic vivax malaria monoinfection." (PMID 31233500, 2019). "Treatment with IL-15C protects against fatal malaria disease in a mouse model of cerebral malaria known as ECM, and this therapeutic effect is dependent on IL-10 production by NK cells." (PMID 31552035, 2019). "Peripheral blood mononuclear cell (PBMC)-derived primary macrophages express increased levels of IL-6, IL-10, IL-1β, and TNF in malaria cases." (PMID 31662766, 2019). "Malaria and/or HAT cases presented significant higher plasma cytokine levels of IFN-γ, TNF-α, IL-6, IL-10 and TGF-β than healthy controls (P < 0.05)." (PMID 31687034, 2019). "The assay was carried out for five plasma cytokines (IFN-γ, TNF-α, IL-6, IL-10, and TGF-β) in HAT and/or malaria cases and healthy controls." (PMID 31687034, 2019). "This was supported by data from pre-clinical malaria models that have shown over-expression of TNF can suppress haematopoiesis in the bone marrow and promote RBC destruction, while IL-10 is thought to enhance hematopoietic activity." (PMID 30809232, 2019). "Higher IFN-γ/IL-10+ specific-CD4+ T cell responses were observed amongst children heavily exposed to malaria compared to children with low exposure indicating that CD4+ T cells may play an important immunomodulatory role in the pathogenesis of childhood malaria." (PMID 30774635, 2019). "In this study, there was significantly increased production of IL-10 and TNF-α in patients with recurrent malaria." (PMID 34557294, 2019). "Malaria and HAT co-infection modified synergistically the pro-inflammatory (IFN-γ, TNF-α) and anti-inflammatory (IL-6, and IL-10) cytokine response than P. falciparum mono-infections." (PMID 31687034, 2019).
malaria (continued). "In patients with severe malarial anemia, PBMCs express elevated levels of IL-10, interferon gamma-induced protein 10 (IP10), macrophage inflammatory protein-1 beta (MIP1β), and MCP2 as compared to uncomplicated malaria or healthy individuals." (PMID 31662766, 2019). "In malaria studies, certain receptors and cytokines are commonly investigated, such as CD163, IL-10, and TNF." (PMID 31662766, 2019). "This study was designed to assess the effect of prenatal exposure to P. falciparum antigens on selected cytokines (IL-10 and IFN-γ) response during clinical malaria episodes in infants aged zero to two years." (PMID 30154871, 2018). "Prenatal exposure to P. falciparum antigens significantly affects IL-10 and IFN-γ responses during clinical malaria episodes in the first two years of life." (PMID 30154871, 2018). "In a prior study with adult malaria patients, we detected IFN-γ+/IL-10+ and IL-10-single positive CD4+ T cells which expressed co-inhibitory molecules in a T cell subset that exerted suppressor function in vitro." (PMID 29555909, 2018). "Thus, plasma APRIL and/or BAFF as IL‐10 levels might reflect the acute phase of malaria." (PMID 29314720, 2018). "It is speculated in this work that IL-10 could, by reducing the number of circulating platelets, prevent the adhesion of parasitized red blood cells to the vascular endothelium, as if thrombocytopaenia could represent a defense mechanism against severe malaria." (PMID 30126413, 2018). "According to this study, IFN-γ, IL-2, IL-5, IL-6 and IL-12 were increased in mild malaria whereas TGF-β, TNF, IL-10 and IL-1β were particularly elevated in CM." (PMID 28775960, 2017). "In conclusion, our data demonstrate that in the context of severe blood‐stage malaria, cDC1 promote the differentiation of parasite‐specific IFNγ+ TNF+ Th1 cells, to the expense of more regulatory IL‐10+ CD4 T cells." (PMID 28935714, 2017). "The combination of biomarkers IL-10 and sTNF-RII have the potential to support malaria diagnosis in pregnancy." (PMID 29255607, 2017). "IL-10 and sTNF-RII were significantly higher at all time-points in malaria-infected women (p < 0.001)." (PMID 29255607, 2017). "Recurrent malaria patients displayed the highest plasmatic IL-10 levels, that correlated directly with the CD4+/CD8+ T-cells ratio and the number of malaria episodes." (PMID 27581163, 2016). "The altered dynamics of IL-10 production during secondary infection compared with primary malaria infection suggested that IL-10 may exert different quantitative and/or temporal roles during the early phases of primary and anamnestic immune responses to malaria." (PMID 27630165, 2016). "And IL-10 correlated significantly with HRP-2, angiopoeitin-2, lactate, arginine, the arginine/ADMA ratio, and the platelet count in those with malaria." (PMID 27385484, 2016). "The production of this cytokine is related to low parasitaemia in the acute phase; however, a balance with anti-inflammatory cytokines, such as IL-10 and TGF-beta, is necessary to reduce severe forms of malaria." (PMID 27435973, 2016). "Furthermore, anti-inflammatory cytokines, included as IL-10, have been found to regulate type 1 responses during infection during a secondary parasitic challenge in the best available mouse model for human severe malaria, demonstrating a regulatory role in the control of pathogenic responses." (PMID 27581163, 2016). "Once parasite replication has been controlled, we and others have shown that anti-inflammatory cytokines, such as IL-10 and TGF-β, are required for prevention of host damage and progression towards severe malaria." (PMID 27418744, 2016). "Given our findings on the heme/hemopexin balance that influences cytokine profiles during severe malaria, we first investigated a possible correlation between EPO, TNF-α, IL-10, IP-10 and MCP-1 plasma levels." (PMID 27441662, 2016).